FOXO1 (forkhead box O1)
Diseases named in the same sentence as FOXO1 in open-access papers (continued):
Sharing a sentence is not in itself a finding about the gene and the disease.
hepatocellular carcinoma (continued). "As T3/TR can trigger rapid, non-transcriptional effects through cross-coupling with the phosphatidylinositol 3-kinase (PI3K)-Akt pathway, we explored whether T3 influences FoxO1 activity in hepatoma cells through a non-genomic mechanism." (PMID 27490929, 2016). "Our results also showed that FOXO1 activation by HDIs upregulated ULK1 expression in hepatoma cells, whereas HDI treatment failed to induce ULK1 expression after FOXO1 knockdown or inhibition." (PMID 32929346, 2020).
type 2 diabetes (82 papers, 2009 to 2026). "For example, previous work has shown that pharmacological inhibition of FOXO1 can ameliorate cardiac defects associated with type 2 diabetes by suppressing PDK4 and thereby increasing PDH activity." (PMID 38769106, 2024). "Meanwhile,FOXO1 gene has been found to be involved in the susceptibility to type 2 diabetes in German18." (PMID 28860538, 2017). "Until now, associations of genetic polymorphisms at SIRT1 and FOXO1 with body mass index (BMI), visceral obesity, insulin sensitivity, type 2 diabetes mellitus (T2DM) and all-cause mortality risk have been described." (PMID 25273948, 2014). "Moreover, FOXO1 functions as an association between transcription and insulin-mediated metabolic control; thus, FOXO1 is a promising genetic target to manage type 2 diabetes." (PMID 28894507, 2017). "Recent work on mice harboring conditional knockout alleles of FoxO1 point to a potential role for FoxO TFs in the pathogenesis of Type 2 diabetes, cancer, and osteoporosis; thus, it is conceivable that the EAK pathway may influence the pathogenesis of these aging-associated diseases." (PMID 20975207, 2010). "Beyond oncology, FoxO1 also influences systemic metabolic regulation, where its upregulation contributes to the development of type 2 diabetes and metabolic dysfunction, pointing to its complex, tissue-specific biology." (PMID 41515404, 2025). "Many studies have shown that in type 2 diabetes, FOXO1 is involved in glucose and lipid metabolism, insulin resistance, and β-cell proliferation, differentiation, and apoptosis, making it an important target for potential therapeutic intervention." (PMID 40951426, 2025). "The disruption of FOXO1-mediated lipid regulation is responsible for the metabolic alterations present in type 2 diabetes mellitus and dyslipidaemic disease." (PMID 41190158, 2025). "In Sprague Dawley rats fed a high-sugar and high-fat diet and injected with low-dose streptozotocin to induce type 2 diabetes, liraglutide (0.2 mg/kg/12 h) for eight weeks had a renoprotective effect by activating forkhead box protein O1 (FoxO1)." (PMID 39768655, 2024). "After rhein administration, studies observed increased activity of superoxide dismutase (SOD) and glutathione peroxidase (GSH-Px), alongside higher FoxO1 protein expression in type 2 diabetic rats." (PMID 39770507, 2024). "FoxO1 inhibitors are being developed for clinical testing in type 2 diabetes and cardiovascular diseases." (PMID 39436708, 2024). "As was mentioned before, TMAO can induce ER stress through PERK and FoxO1 activation, leading to the expression of INSR and insulin cellular resistance and elevating the risk of developing type 2 diabetes." (PMID 36830968, 2023). "Accordingly, FoxO-1 mRNA levels were found to be increased in the islets of patients with type 2 diabetes in clinical studies." (PMID 36596838, 2023). "FOXO1 expression in skeletal muscle has been reported to be significantly upregulated in patients with type 2 diabetes compared with healthy individuals and to be decreased by resistance-training exercises in the skeletal muscle of healthy individuals." (PMID 37016292, 2023). "These interventions include the use of the PDK4 inhibitor dichloroacetate, and chemical inhibition of FoxO1 transcriptional activity (which drives increased PDK4 expression in type 2 diabetes), both of which improved diastolic function in diabetic rodents." (PMID 35924321, 2022). "Resveratrol can regulate SIRT1 and FOXO1, improve islet function, and reduce blood glucose levels in macaques with type 2 diabetes." (PMID 35685602, 2022). "Foxo1 is a key regulator that mediated by insulin under physiological conditions in type 2 diabetic mice." (PMID 34899339, 2021). "The FOXO1 specific small molecular compound AS1842856 has been analyzed as therapeutic drug for the treatment of type 2 diabetes in mice, and has been tested in regard of pulmonary hypertension and bone development." (PMID 31591479, 2020).
type 2 diabetes (continued). "Down regulation of the PEPCK gene can diminish gluconeogenesis and its expression is commonly up-regulated in type 2 diabetes, with FOXO1 known to inhibit PEPCK expression to counteract its effect." (PMID 30390669, 2018). "Given its association with MetS processes, therapeutic strategies have also been proposed to treat type 2 diabetes through FoxO1/3a signaling." (PMID 30459740, 2018). "Their analysis emphasizes how crucial FOXO1 is for regulating lipid homeostasis and suggests that changes in its activity may be a factor in the lipid abnormalities seen in type 2 diabetes." (PMID 41190158, 2025). "Fourthly, curcumin also enhanced Akt phosphorylation and inhibited Foxo1 acetylation, indicating that it might reduce OS damage of type 2 diabetes and protect cardiomyocyte from apoptosis by modulating Sirt1‐Foxo1and PI3K‐Akt pathways." (PMID 32961025, 2020). "Importantly, new selective FOXO1 inhibitors for the treatment of type 2 diabetes have recently been developed by AstraZeneca." (PMID 31557894, 2019). "The findings reveal that SIRT1/FOXO1 may involve in the initiation and development of DN in Han Chinese patients with type 2 diabetes." (PMID 28860538, 2017). "FoxO1 regulation of VEGF-A/islet vascular formation may contribute to compensatory β cell hyperplasia against peripheral insulin resistance, a hallmark of type 2 diabetes." (PMID 22384192, 2012). "Mechanically, the deacetylation of PGC-1α or FOXO1 modulated by SIRT1 is tightly linked with enhanced transcriptional activation in gluconeogenesis and glycolysis, resulting in increased hepatic glucose production and further contributing to the development of type 2 diabetes." (PMID 34738906, 2021). "In vitro and in vivo experiments confirm, Puerarin could enhance the phosphorylation of Foxo1 by activating PI3K/Akt signaling pathway in liver tissues of type 2 diabetes rates and elevating the pFoxo1/Foxo1 protein and mRNA expressions, and further inhibiting the expression of G6pase and PEPCK." (PMID 35058775, 2021). "Our results suggested that FoxO1 may exert its activity partially through the regulation of Pdcd2l in palmitate-induced β cell apoptosis and could help to clarify the molecular mechanisms of β cell failure in type 2 diabetes." (PMID 27861641, 2016). "Type 2 diabetes, hyperlipidemia, and CKD can contribute to FOXO1 upregulation in the EDL of SDT fatty rats." (PMID 37016292, 2023). "The results of liquid chromatography/electrospray ionization/tandem mass spectrometry revealed that high FTO expression in type 2 diabetes mellitus (T2DM) patients accompanied by increased mRNA expression levels of key genes of glucose metabolism (FOXO1, G6PC, and DGAT2)." (PMID 36830642, 2023). "It is notable that several of the altered MAM proteins are associated with genes that have been discovered to play roles in both Type 1 and Type 2 diabetes (e.g., STAT4 and FOXO1)." (PMID 36139394, 2022). "Previous studies have shown that N1-methylnicotinamide (MNAM) regulates insulin sensitivity and hepatocyte gluconeogenesis in mice with type 2 diabetes by activating SIRT1 and inhibiting the acetylation of FOXO1." (PMID 36295866, 2022). "This study is aimed at establishing models of obese type 2 diabetes in vitro and in vivo, observe the effect of MNAM on hepatic insulin sensitivity and glucose metabolism, and explore the regulation of the SIRT1/FOXO1 pathway." (PMID 32280711, 2020). "Besides, MNAM also improves hepatic insulin sensitivity of mice with type 2 diabetes via activation of SIRT1 and inhibition of forkhead box O1 (FOXO1) acetylation." (PMID 38029302, 2024). "FOS, IGF1R, IGF2, FOXO1, and NTF3 might target “TGF-β signaling pathway”, “the hedgehog signaling pathway”, “retinol metabolism”, or “type II diabetes mellitus” pathways respectively." (PMID 32694937, 2020).
type 2 diabetes (continued). "Additionally, renal pathological damage improved, suggesting that rhein may protect the kidneys of type 2 diabetic rats by alleviating renal oxidative stress and regulating the PI3K/Akt/FoxO1 signaling transduction pathway." (PMID 39770507, 2024). "Thus, the P. frutescens leaf polysaccharide could improve type 2 diabetes-induced rat liver injury by inhibiting oxidative stress and inflammation, while regulating activation of the SIRT1/FoxO1 signaling pathway." (PMID 38585610, 2024). "Based on the negative role of FoxO-1 in insulin action, FoxO-1 inhibitors may be applicable as a new therapeutic approach to treat metabolic disorders, including type 2 diabetes." (PMID 36596838, 2023). "Collectively, all these data indicate that GPS significantly inhibits gluconeogenesis by regulating the PI3K/AKT/FOXO1 signaling pathway in liver of the diabetic mice, indicating that this may be the potential mechanism by which GPS treatment improves symptoms of type 2 diabetes." (PMID 37601073, 2023). "Endurance exercise training might alleviate muscle wasting by preventing muscle degradation through the inhibition of the FOXO1–MuRF1 pathway and by increasing the angiogenic response in the EDL muscle in type 2 diabetes with hypertension, hyperlipidemia, and CKD." (PMID 37016292, 2023). "Based on the ceRNA network, we also discovered that FOS, IGF1R, IGF2, FOXO1, and NTF3 might target the “TGF-β signaling pathway”, “the hedgehog signaling pathway”, “retinol metabolism”, or “type II diabetes mellitus” pathways respectively, thereby modulating the subsequent development of ICC." (PMID 32694937, 2020).
gastric cancer (65 papers, 2011 to 2024). A primary or metastatic malignant neoplasm involving the stomach. "FOXO1-mediated M1 polarization has been demonstrated in gastric cancer, periodontal bone loss, and NAFLD and can be investigated as potential pathogenesis of AAA." (PMID 35990982, 2022). "CircMRPS35 expression is positively associated with FOXO1 and FOXO3a expression in patients with gastric cancer." (PMID 32164722, 2020). "We next investigated the clinical associations among circMRPS35, FOXO1 and FOXO3a in gastric cancer tissues." (PMID 32164722, 2020). "The low expression of FOXO1 or FOXO3a was strongly associated with poor survival of gastric cancer patients." (PMID 32164722, 2020). "In fact, the upregulation of FOXO1 phosphorylation in gastric cancer correlates with better outcomes and FOXO1-activating mutations in B-cell lymphomas contribute to cancer progression." (PMID 32629884, 2020). "Altogether, our study not only provides the pivotal roles of circMRPS35 in governing histone modification to activate FOXO1/3a pathways, but also reveals circMRPS35 as a promising diagnostic marker and therapeutic target to combat gastric cancer." (PMID 32164722, 2020). "The expression of inactivated form of phosphorylated FOXO1 was inversely related to lymph node metastasis and positively associated with a longer survival time in patients with early-stage gastric cancer." (PMID 29221208, 2017). "Immunohistochemical tissue array analysis showed that JNK activation was positively associated with FOXO1 inactivation in gastric cancer specimens, which indicates an inverse relationship between the activations of JNK and FOXO1 (P < 0.001)." (PMID 27268017, 2016). "Our results indicate that JNK activation, alone or along with FOXO1 inactivation, is a candidate prognostic marker for the early gastric carcinoma and positively associated with pro-proliferation genes and FOXO1 inactivation." (PMID 27268017, 2016). "In the present study, our results of immunohistochemical tissue array analysis and in vitro cell culture experiments suggest that FOXO1 in gastric cancer cells is implicated in gastric tumor angiogenesis." (PMID 21696576, 2011). "Taken together, the novel circMRPS35 governing histone modification for FOXO1/3a activation, may serve as a promising diagnostic marker and therapeutic target to combat gastric cancer." (PMID 32164722, 2020). "In addition, the association between JNK and FOXO1 was examined in human gastric cancer specimens and gastric cancer cells." (PMID 27268017, 2016). "Although previous studies suggested that FOXO1 inactivation may contribute to the development of gastric cancer, information on the molecular mechanisms underlying FOXO1 activation in gastric cancer is limited." (PMID 27268017, 2016). "Our results indicate that JNK activation may serve as a valuable prognostic factor in gastric cancer, and that it is implicated in gastric tumorigenesis, at least in part, through FOXO1 inhibition." (PMID 27268017, 2016). "In gastric cancer, S256-phosphorylated FOXO1 correlates with higher overall survival and lower tumor angiogenesis, suggesting that activated FOXO1 supports tumor growth and metastasis." (PMID 38519029, 2024). "In gastric cancer, FOXO1 also suppresses VEGFA and other angiogenesis‐related molecules, inhibiting vascular formation in the tumour area and enhancing immune responses against tumour cells." (PMID 38899748, 2024). "Similar findings implicated that exosomal miR-155 and miR-135b from culture medium of gastric cancer cells also enhanced angiogenesis in GC by inhibiting the expression of transcription factor FOXO3a and FOXO1." (PMID 33430032, 2021). "ANCR can inhibit the expression of FoxO1 in THP-1 cells by promoting the ubiquitination and degradation of FoxO1, which ultimately promotes the invasion and metastasis of gastric cancer cells." (PMID 35011565, 2021).
gastric cancer (continued). "A study by Choi and colleagues showed that theinteraction between LGR5 and FOXO1 genes play an important role in the development of gastric cancer." (PMID 33718760, 2021). "In summary, circMRPS35 suppresses the behaviors of gastric cancer cells through transcriptional activation of FOXO1 and FOXO3a." (PMID 32164722, 2020). "In gastric cancer it is clear that FOXO1 functions to inhibit angiogenesis, and gastric carcinomas with pFOXO1 (inactive proteoform) are associated with higher expression of angiogenic drivers such as HIF1α and vascular endothelial growth factor (VEGF)." (PMID 33088284, 2020). "Collectively, these data strongly indicate that circMRPS35-mediated FOXO1 and FOXO3a signaling plays a crucial role in gastric cancer." (PMID 32164722, 2020). "miR-9 also targets genes encoding tumor suppressor factors, such as FOXO1 (Forkhead box protein O1) and CDX2 (caudal-related homeobox 2), increasing cell growth and proliferation, respectively, in breast and gastric cancer." (PMID 32111074, 2020). "For example, FOXO1 was reported to inhibit tumor sphere formation capacity of gastric cancer cells through regulation of LGR signaling." (PMID 32047567, 2020). "Our findings not only reveal the pivotal roles of circMRPS35 in governing histone modification in anticancer treatment, but also advocate for triggering circMRPS35/KAT7/FOXO1/3a pathway to combat gastric cancer." (PMID 32164722, 2020). "In tumor biology, FOXO1 is typically down-regulated or depleted in malignant tissues in cervical cancer, ovarian cancer, renal clear cell carcinoma, and gastric cancer." (PMID 31027497, 2019). "MicroRNA-96 expression induced by low-dose cisplatin or doxorubicin regulates chemosensitivity, cell death, and proliferation in gastric cancer SGC7901 cells by targeting FOXO1." (PMID 31395078, 2019). "FoxO1 is a transcriptional factor that plays a key role in the development and progression of gastric cancer." (PMID 31767027, 2019). "Recent work has shown that miR-196 targets FoxO1 in cervical cancer cells and p27 in gastric cancer cells." (PMID 27880728, 2017). "miR-370 was reported to be upregulated and to function as an oncogene by targeting FoxO1 in human prostate and gastric cancers." (PMID 29254166, 2017). "Further, the combination of JNK inhibition and FOXO1 silencing partially restored the colony forming capability of gastric cancer cells compared to JNK inhibition alone." (PMID 27268017, 2016). "Though the regulatory connection between miR-132-3p and FOXO1 has already been reported in gastric cancer cells, the direct targeting of miR-132-3p with GDF5 and SOX6 was newly discovered." (PMID 27556448, 2016). "In the present study, immunohistochemical tissue array analysis of gastric cancer specimens showed that JNK activation was positively correlated with FOXO1 inactivation." (PMID 27268017, 2016). "The present study was performed to evaluate the biological significance of JNK alone or in combination with FOXO1 in human gastric cancer regarding patient survival rate and tumor growth." (PMID 27268017, 2016). "In gastric cancer, FOXO1 inactivation occurs and increases gastric cancer cell proliferation and angiogenesis." (PMID 27268017, 2016). "Literature mining informed us that FOXO1 and EGR1 have been implicated in HCC, and ZIC1 is down-regulated in gastric cancer and has been proved to be a tumor suppressor gene in colorectal cancer." (PMID 24278165, 2013). "FOXO1 expression was suppressed by transfecting FOXO1 shRNA into SNU-638 gastric cancer cells, and subsequently, cells were cultured under normoxic or hypoxic conditions." (PMID 21696576, 2011). "In the present study, FOXO1 expression was inhibited by infecting gastric cancer cells (SNU-638) with a shRNA-expressing lentivirus." (PMID 21696576, 2011). "Since we found previously that AKT activation induced angiogenesis in gastric cancer xenografts, our results suggest that AKT/FOXO1 pathway is involved in angiogenesis in gastric cancer." (PMID 21696576, 2011).